KISS1 (KiSS-1 metastasis suppressor)
Diseases named in the same sentence as KISS1 in open-access papers (continued):
Sharing a sentence is not in itself a finding about the gene and the disease.
placenta previa (1 paper, 2024). "The samples in the control and placenta previa group were categorized according to their gestational weeks and divided into 2 separate subcategories as the 2nd and 3rd trimester, and the KISS1 concentration level was evaluated." (PMID 38996103, 2024). "The evaluation of KISS1 concentration in serum revealed a significant decrease in the placenta previa group compared to the control group (P < .001)." (PMID 38996103, 2024). "Results from biochemical, immunohistochemical, and genetic analyses consistently indicated significantly reduced KISS1 expression in patients with placenta previa." (PMID 38996103, 2024). "These collective findings suggest a lower expression of KISS1 in patients with placenta previa, potentially impairing their ability to regulate trophoblast invasion and leading to an abnormal course of placental invasion." (PMID 38996103, 2024). "These consistent outcomes support the conclusion that KISS1 expression is diminished in patients with placenta previa." (PMID 38996103, 2024). "Particularly, lower concentration of KISS1 was observed in the third trimester in the placenta previa group." (PMID 38996103, 2024). "In this study, a decrease in KISS1 gene expression levels was observed in patients with placenta previa, consistent with the biochemical data." (PMID 38996103, 2024). "In this study, the diminished levels of KISS1 expression in patients with placenta previa is observed when compared to the control group." (PMID 38996103, 2024). "Nonetheless, our study revealed lower levels of both placental KISS1 expression and plasma KISS1 expression in the placenta previa group compared to the control group." (PMID 38996103, 2024). "As a result of the evaluation of KISS1 concentration level in serum, a significant decrease was observed in the placenta previa group compared to the control group (P < .001)." (PMID 38996103, 2024). "Both biochemical and genetic analyses consistently indicated significantly reduced KISS1 expression in individuals with placenta previa." (PMID 38996103, 2024). "This study aimed to elucidate the possible role of KISS1 in diagnosing placenta previa in the first 20 weeks of pregnancy by investigating KISS1 expression levels in plasma and placenta sample." (PMID 38996103, 2024). "In contrast, patients with placenta previa showed a decline in KISS1 levels during the third trimester compared to the second trimester." (PMID 38996103, 2024). "Analysis of KISS1 gene expression revealed a substantial 0.043-fold reduction in the placenta previa group compared to the control group, demonstrating a highly significant statistical difference (P < .001)." (PMID 38996103, 2024). "Furthermore, our analysis of plasma levels revealed that KISS1 expression during the third trimester was lower than in the second trimester for patients with placenta previa." (PMID 38996103, 2024). "Our study’s examination of patients with placenta previa suggests that determining KISS1 levels could play an effective role in diagnosing placenta previa." (PMID 38996103, 2024). "KISS1 gene expression level 0.043-fold decreased in the placenta previa group (P < .001)." (PMID 38996103, 2024). "Larger-scale studies measuring KISS1 in patients with placenta previa could shed light on its effectiveness in diagnosing the condition." (PMID 38996103, 2024). "Investigating markers associated with placental invasion, apoptotic and antiapoptotic processes may provide insights into the potential roles of KISS1 in placenta previa." (PMID 38996103, 2024). "KISS1 may play a critical role in the etiology of placenta previa." (PMID 38996103, 2024). "In conclusion, KISS1 may have a potential role in the etiology of the placenta previa." (PMID 38996103, 2024). "Moreover, employing KISS1 replacement therapy in experimental animals with a placenta previa model may offer insights into KISS1’s potential roles in the etiology of placenta previa and its preventive effects." (PMID 38996103, 2024).
squamous cell carcinoma (1 paper, 2021). A carcinoma arising from squamous epithelial cells. "First, we found that Kiss1 and Kiss1R were lowly expressed in squamous cell carcinoma tissues and highly expressed in nonkeratinizing squamous cell carcinoma tissues by immunohistochemistry." (PMID 35117986, 2021). "This work showed that KISS1 and KISS1R were lowly expressed in squamous cell carcinoma tissues and highly expressed in nonkeratinizing squamous cell carcinoma tissues by immunohistochemistry." (PMID 35117986, 2021). "In this study, we identified that the expression of KISS1 and its receptor KISS1R in squamous cell carcinoma tissues was lower than that of nonkeratinizing squamous cell carcinoma tissues." (PMID 35117986, 2021).
steatosis (1 paper, 2022). Increased lipid within the cytoplasm of cells. "Since our data revealed that KISS1R signaling inhibits steatosis in vivo, a direct effect of KP on hepatic lipogenesis was examined using isolated primary hepatocytes; we observed that they expressed KISS1 in a punctate pattern typical of secreted peptides." (PMID 35349482, 2022).
tumor (90 papers, 2003 to 2026). "Increased KISS1 mRNA expression is associated with reduced metastatic potential, potentially through the inhibition of tumor cell migration and invasion." (PMID 40430029, 2025). "The activation of KiSS-1 signalling has been associated to inhibition of cancer cells invasion, metastasis formation and tumor recurrence." (PMID 38732265, 2024). "The presence of metastasis and tumor size was negatively associated with pre-operative KISS1 expression; patients with low KISS1 expression had shorter survival time than those with high expression." (PMID 30123188, 2018). "Through an immunohistochemical analysis of a tumor microarray, this study also showed that lymph node positive status is associated with high KISS1 protein levels." (PMID 30123188, 2018). "Positive expression of KiSS-1 was inversely associated with invasion, tumor size, LNM stage, and TNM stage." (PMID 30021598, 2018). "It has been reported that down regulation of KiSS1 was associated with more aggressive ovarian cancer and caused tumor growth and invasion becoming a strong prognostic factor in gastric carcinoma patients." (PMID 29721201, 2018). "One explanation for this behavior is that the loss of TCF21 decreases the activation of the known metastatic suppressor, KISS1, causing an increase in the metastatic potential of the tumor." (PMID 28476165, 2017). "Down-regulation (for example, through homozygous deletion, promoter methylation, or mutation) of KiSS-1 can increase tumor invasion and metastasis." (PMID 28253891, 2017). "(ii) In contrast, significantly down-regulated genes from another group were associated with tumor metastasis suppression (KISS1), retinoblastoma (Rb) gene positive regulator (CCND1), and a canonical Wnt antagonist (LRP6 through DDK1)." (PMID 26079538, 2015). "The analysis of the expression patterns of KiSS-1 by in situ hybridisation on tissue microarrays confirmed the loss of KiSS-1 in the progression of the disease, and was associated with tumour stage, grade, and overall survival." (PMID 14676790, 2003). "Moreover, KISS1 is significantly associated with immune cell infiltration and immunosuppressive cells, suggesting its crucial role in modulating tumor immunotherapy." (PMID 41523580, 2026). "However, in some cancer types, the KISS1/KISS1R pathway has been associated with tumor progression and increased metastatic ability." (PMID 37640761, 2023). "Moreover, loss of KiSS-1 protein expression by tumor cells has been associated with a more aggressive phenotype." (PMID 29662466, 2018). "The loss of KiSS1 by tumor cells has been associated with a metastatic phenotype but the mechanistic insights of this process are still unknown." (PMID 29721201, 2018). "Nevertheless, Kaplan-Meir survival data indicated that patients with EOC KISS1-negative tissues had a lower survival rate compared to KISS1-positive patients, and among these patients, KISS1 protein expression was inversely associated with tumor grade and stage." (PMID 30123188, 2018). "Previous studies have shown that KISS1 was closely associated with the prognosis of cancer patients, and the decreased expression of KISS1 results in increased metastatic potential and aggressive tumor progression." (PMID 27145368, 2016). "Kisspeptin, encoded by KiSS1 gene was first considered as a tumor metastasis suppressor; however, it plays a major role in regulating the hypothalamic-pituitary-gonadal axis, so many studies have analyzed polymorphisms or haplotypes in KiSS1 gene particularly in central precocious puberty." (PMID 25810563, 2015). "Here, we conducted a pancancer study using public databases to acquire a more efficient understanding of KISS1 in terms of its molecular mechanisms and predictive value in tumor biology." (PMID 41523580, 2026).
tumor (continued). "To investigate the potential role of KISS1 in the tumor microenvironment (TME), we explored the relationship between KISS1 and the level of immune infiltration in various cancers from TCGA using three immune scores and selected the four most significant ones." (PMID 41523580, 2026). "Our study confirmed the therapeutic and prognostic potential of KISS1 and indicates the potential as an immunotherapy target for tumor metastasis." (PMID 41523580, 2026). "REN expression was positively correlated with KISS1 expression both in JGCTs and other tumor types, including THYM, THCA, TGCT, and KIRP." (PMID 42038360, 2026). "In some tumour types, the KISS1R/KISS1 pathway is upregulated in the primary tumour and serves as a tumorigenesis and metastasis suppressor." (PMID 39775975, 2025). "Surprisingly, studies reported very low KISS1 expression in tumor cells, whereas the highest expression was seen in the human placenta, followed by the pancreas, liver, and small intestine." (PMID 40430029, 2025). "A recent study supports an inverse relationship between KiSS-1 expression and tumor progression, since stage I–II NSCLCs showed higher levels of KiSS-1 than III-IV NSCLCs." (PMID 38732265, 2024). "KISS-1 is secreted by tumor cells in the tumor microenvironment in pathological states but is secreted from placental villous trophoblasts during placental development, but is secreted from placental villous trophoblasts during placental development." (PMID 37024487, 2023). "KISS1 has been reported to act as a context‐dependent inhibitor of metastasis or tumour promoter in a range of cancers, as well as a disruptor of proliferation and invasion in PM cell lines." (PMID 36740402, 2023). "In summary, further studies are needed to develop a more optimized KISS1 radiotracer with a higher tumor uptake and tumor-to-background ratio for clinical applications." (PMID 38256878, 2023). "We first determined the expression of KISS1R, the target of the newly developed [68Ga]KISS1-54 radiotracer in selected human tumor cell lines of different tumor types." (PMID 38256878, 2023). "In particular, deeper investigations aimed at clarifying the role played by the expression of KiSS1 and KiSS1R as well as the contribution of secreted KiSS1 by the tumor are needed." (PMID 37790750, 2023). "A recent body of evidence reports that KISS-1 is considered to be a potential tumor suppressor in a number of different tumors and is involved in cell proliferation, migration and invasion by targeting the MAPK/ERK and P50/MMP-9 pathways." (PMID 37024487, 2023). "The results of a previous study as well as this study show that the effects of KISS-1 were demonstrated against pathological angiogenesis in tumor models as well as against physiological angiogenesis occurring during organ development." (PMID 37024487, 2023). "miR-124 enhances the expression of the KiSS1 (Kisspeptin 1) gene reducing the proliferation of tumor cells, their invasion, and migration." (PMID 36362406, 2022). "The KISS1 gene product functions as tumor metastasis suppressor and is reported to act after binding with human orphan G protein-coupled receptor (hOT7T175 or GPR54, KISS1R)." (PMID 35117986, 2021). "Although the loss of KISS1 and KISS1R expression has been associated with tumor progression and poor prognosis in various cancers, the mechanism underlying this phenomenon is still unclear." (PMID 35117986, 2021). "Healthy mice had significantly higher melatonin level (16.09 ± 1.26 ng/L vs 9.59 ± 0.98 ng/L, P = 0.002, t = 3.440) and significantly lower Kiss1 expression than tumor-bearing mice (3.08 ± 1.15 vs 11.96 ± 3.07, P = 0.003, t = 3.280)." (PMID 32118379, 2020). "Our results showed that melatonin and Kiss1 were important tumor suppressors and were highly affected by daylight." (PMID 32118379, 2020).
tumor (continued). "Recently, we reported that KISS1/KISS1R expression are upregulated in TNBC patient tumor biopsies compared with healthy breast tissue and that KISS1R signaling induces a drug-resistant phenotype in TNBC25." (PMID 32034133, 2020). "KISS1/KISS1R expression are upregulated in TNBC patient tumor biopsies and high KISS1 expression has been shown to correlate with increase in lymph node metastasis." (PMID 32034133, 2020). "Tumor volume was inversely proportional to melatonin levels and directly proportional to Kiss1 expression levels." (PMID 32118379, 2020). "There was a strong inverse correlation (correlation coefficient = -0.766, P = 0.004) between melatonin levels and tumor volumes and a strong positive correlation (correlation coefficient = 0.849, P = 0.001) between Kiss1 expression and tumor volumes." (PMID 32118379, 2020). "For example, KISS1 is one of the candidate genes involved in the dormancy state, the phase of tumor progression in which patients appear asymptomatic and the disease remains in a state of latency for a variable period of time." (PMID 31336647, 2019). "In fact, KISS1 methylation was related to tumor-grade metastasis, predicted recurrence, and disease-free and overall survival." (PMID 31336647, 2019). "The loss of KISS1 expression in CRC has been reported; KISS1 expression is low in various tumor tissues, which can enhance the growth, invasion, and migration of tumor cells." (PMID 31803739, 2019). "Decreased expression of KiSS-1R seems to attenuate signaling of the KiSS-1/KiSS-1R system, possibly leading to tumor growth." (PMID 29760678, 2018). "Results have demonstrated that the normal expression of KiSS-1 can suppress tumor cell growth, motility, and migration." (PMID 30021598, 2018). "Although the anti-metastatic role has not been studies extensively as compared to the reproductive function, nevertheless a large body of literature documented the involvement of the KiSS-1/KiSS-1R system in supporting tumor progression." (PMID 29760678, 2018). "Antagonizing the Warburg effect is, therefore, an attractive strategy to limit tumor growth, as documented by the impact of the metastasis suppressor KISS1 gene that enhances mitochondrial biogenesis and OXPHOS." (PMID 30456364, 2018). "Recent papers attribute to KiSS-1/KiSS-1R complex a diverse function from that observed in other tumor types." (PMID 29760678, 2018). "The results indicated that positive expression of KiSS-1 was inversely correlated with tumor size, invasion, LNM stages, and TNM stages." (PMID 30021598, 2018). "Similar observations on tumor progression, metastasis, and survival in different human cancers make KISS1 an interesting target for controlling metastasis in a therapeutic context." (PMID 28207895, 2017). "Overall, studies of VM, ALDH1, KiSS-1, and MACC1 in association with tumor metastasis and prognosis suggest that these factors affect cancer progression; however, the associations among VM, ALDH1, KiSS-1, and MACC1 in EOC has not been widely reported." (PMID 28253891, 2017). "The rate of KiSS-1+ expression was inversely related to tumor grade, LNM, implantation, and FIGO stage." (PMID 28253891, 2017). "Findings in this study also demonstrated that KiSS-1 expression was significantly lower in EOC tissues than in control tissues, and its expression was inversely associated with tumor grade, LNM, implantation and FIGO stage." (PMID 28253891, 2017). "KP10, a short 10-amino acid peptide of KiSS1, can also inhibit proliferation and migration of tumor cells in vitro and in vivo." (PMID 27287327, 2016). "By multivariate analysis, tumor size, expression of Kiss-1 in positive SLN and the size of SLN metastasis remained significantly predictive of NSLN status (p<0.05)." (PMID 25111296, 2014). "We previously showed that KISS1 is secreted by tumor cells and this property is critical for its role in metastasis suppression." (PMID 24454770, 2014).